SIRT3 (sirtuin 3)
Diseases named in the same sentence as SIRT3 in open-access papers (continued):
Sharing a sentence is not in itself a finding about the gene and the disease.
heart failure (continued). "More recently and in agreement with our results here, a preliminary report supports that the cardiomyocyte-specific deletion of SIRT3 promotes heart failure." (PMID 36460774, 2023). "The adipokine omentin improves myocardial infarction-induced heart failure by activating mitophagy via the SIRT3/FOXO3 pathway." (PMID 36675125, 2023). "Omentin 1 improves myocardial ischemia-induced heart failure by relying on SIRT3/FOXO3a for mitochondrial dynamic homeostasis and mitophagy." (PMID 38012584, 2023). "It is a general understanding that SIRT3's deacetylase activity plays a major protective role against heart failure by regulating cardiac ATP levels." (PMID 35369299, 2022). "Metformin augments SIRT3, thereby improving heart failure post-myocardial infarction by enhancing cardiac metabolism and reducing apoptosis." (PMID 35369299, 2022). "ATP synthase hyperacetylation can affect cardiac energy metabolism and is regulated by Sirt3 in heart failure." (PMID 36160705, 2022). "In addition, SIRT3 deficiency impairs mitochondrial oxidation and endothelial function, but also decreases angiogenic growth factors and induces microvascular rarefaction, resulting in cardiac energy depletion, contractile dysfunction, heart failure and impaired recovery." (PMID 34829803, 2021). "SIRT3 is involved in the regulation of mitochondrial deacetylation, thus preventing ventricular dysfunction and heart failure." (PMID 33806509, 2021). "Sirt3 activity impairment has been found to increase the lysine acetylation of mitochondrial proteins due to oxidative stress in a heart-failure animal model." (PMID 33233476, 2020). "Complex I deficiency has also been shown to increase mitochondrial protein acetylation and accelerate heart failure, via SIRT3-mediated hyperacetylation." (PMID 32606301, 2020). "A growing body of evidence suggests that impaired SIRT3 activity plays a role in many heart disorders, including heart failure." (PMID 31866862, 2019). "Emerging evidence suggest the regulatory roles of SIRT3 in the regulation of EC metabolism, angiogenesis and heart failure." (PMID 30873415, 2019). "In rodent heart failure model, the expression of SIRT3 decreased with increased myocardial mitochondrial protein lysine acetylation in the heart, suggesting that SIRT3 activity was impaired." (PMID 31866862, 2019). "Inhibition of this deacetylation using SIRT3 deletion caused increased death when mice were subject to stress by transaortic constriction, while heart failure decreased the expression of SIRT3 and increased CyPD acetylation." (PMID 30558250, 2018). "It has previously been reported that epicatechin-rich cocoa increased the expression of SIRT3 in the skeletal muscle of patients with type II diabetes and heart failure." (PMID 30018977, 2018). "In contrast though, when hypertrophy progresses to heart failure, or in doxorubicin-induced heart failure, expression of SIRT3 was decreased." (PMID 27790619, 2016). "Our data showed that, compared with wild-type mice, SIRT3-KO mice subjected to TAC had a propensity to develop heart failure and lipid accumulation in the mitochondria." (PMID 25748450, 2015). "All of these results indicated that the SIRT3-KO mice were inclined to develop heart failure and lipid metabolism disorders." (PMID 25748450, 2015). "We therefore further tested our notion that impaired mitochondrial function exacerbates diet-induced heart failure by feeding SIRT3 KO mice a HFD, creating a model of metabolic/mitochondrial stress." (PMID 25782072, 2015). "Biological functions of SIRT1/SIRT3 are described in this review, mainly from the viewpoint of translation into therapy for heart failure." (PMID 22622703, 2012). "Since derangement of these physiological processes underlies the development/progression of heart failure, pharmacologic activation of SIRT1 and/or SIRT3 potentially ameliorates the disease." (PMID 22622703, 2012). "It revealed a 46% reduction in SIRT3 levels in obese heart failure patients." (PMID 41276460, 2025).
heart failure (continued). "Similarly, in mouse hearts, SIRT4 inhibits SIRT3-mediated SOD2 activation potentially by competitively interacting with Mn-SOD for binding to SIRT3, leading to higher ROS levels and heart failure." (PMID 40799515, 2025). "This suggests that SIRT3 reduction mediates cardiac failure in obese patients, indicating that SIRT3 may be a potential target for mitigating ventricular dysfunction and slowing heart failure progression." (PMID 41276460, 2025). "Our results demonstrate that SIRT3 activation may be a novel therapeutic target for improving exercise capacity in patients with heart failure." (PMID 40511632, 2025). "The results of the echocardiography analysis indicated that 2-APQC may improve ISO-induced cardiac dysfunction and exert cardioprotective effects by activating SIRT3 in ISO-induced heart failure mouse model." (PMID 38744811, 2024). "However, SIRT3 expression decreases upon progression to decompensated hypertrophy or heart failure, suggesting that it is responsive to changes in energy demand." (PMID 37237500, 2023). "Besides, in heart failure, the downregulation of SIRT3 disturbed oxidative phosphorylation and resulted in the energy metabolism imbalance of cardiomyocytes." (PMID 36192726, 2022). "So, is the role of OPA1 also affected by Sirt3 in pressure overload-induced heart failure?" (PMID 35592397, 2022). "SIRT3 could delay the progression of heart failure through improvement of mitochondrial function including mitochondrial quality control, mitochondrial biosynthesis, oxidative phosphorylation, and fatty acid oxidation." (PMID 36192726, 2022). "Since ketogenesis may serve as an essential energy source in failing hearts, SIRT3-dependent upregulation of ketogenesis may function as a “rescue strategy” in heart failure." (PMID 35369299, 2022). "Thus, SS31 can alleviate pressure overload-induced heart failure through Sirt3-mediated mitochondrial fusion." (PMID 35592397, 2022). "Furthermore, increased LCAD acetylation and reduced SIRT3 expression is also evident in rat models of heart failure." (PMID 35369299, 2022). "Intervention and treatment of Sirt3 may inhibit oxidative stress damage and delay or even reverse cardiac remodeling in heart failure." (PMID 34095262, 2021). "Taken together, our data suggested that a reduction of SIRT3 may contribute to Ang‐II‐mediated cardiac remodelling and heart failure." (PMID 32463172, 2020). "Our results show that Sirt3 can act as a therapeutic target in the treatment of heart failure." (PMID 33014281, 2020). "LCZ696 may mitigate myocardium oxidative stress and apoptosis in pressure overload-induced heart failure by regulating the Sirt3/MnSOD pathway." (PMID 33014281, 2020). "Also, the application of specific small molecules for activating Sirt3 can be a novel strategy to hinder the progression of pathological hypertrophy into heart failure." (PMID 33014281, 2020). "In addition, activation of SirT3 accelerates glucose metabolism via upregulation of PPARα, and SirT3-induced metabolic reprogramming has been shown to sustain cardiomyocyte function in a mouse model of heart failure." (PMID 32721927, 2020). "The importance of SIRT3 is also demonstrated during the development of heart failure." (PMID 31866862, 2019). "Indeed, SIRT3 expression is reduced and global mitochondrial protein lysine acetylation is increased in rodent models of heart failure, suggestive of impaired SIRT3 activity." (PMID 27790619, 2016). "Judging from the fundamental involvement of mPTP opening in myocardial cell death and the development of heart disease, modulation of Sirt3 could be an important modality for medical treatment of heart failure." (PMID 21248376, 2011). "We previously showed that SIRT3, a major regulator of mitochondrial enzyme deacetylation that plays an important role in regulating mitochondria energy production and cardiac remodeling in heart failure, is reduced in the hearts of male HFD-Offs as early as 21–23 days after birth." (PMID 40112092, 2025).
heart failure (continued). "Besides, silencing SIRT3 may sensitize overload-induced heart failure by worsening cardiomyocyte glucose utilization, whereas the impaired SIRT3-mediated endothelium cell metabolism could even result in cardiac diastolic dysfunction." (PMID 36093141, 2022). "Besides, studies have shown that the dysfunction of Sirt3 is associated with the progression of heart failure, hypertension and other CVD, and enhancing Sirt3 function could alleviate the symptoms of CVD." (PMID 36559254, 2022). "Clinical studies have shown that the Sirt3 level decreases by 40% in 65-year-old people, which may be closely related to the occurrence of many multiple senile diseases, such as hypertension, atherosclerosis, and heart failure." (PMID 33014281, 2020). "Therefore, development of drugs targeting at up-regulation of SIRT1/SIRT3 may be an effective direction for the treatment of heart failure." (PMID 31866862, 2019). "Oroxylin A (OA), which is derived from the root of Scutellaria baicalensis, was found to be a SIRT3 activator in an in vitro model of cardiac myocyte insulin resistance and plays roles in preventing myocardial contractile function and improving myocardial fibrosis and heart failure." (PMID 29643974, 2018). "Thus, both, reduced expression of SIRT3 and a decrease in NAD+ availability may contribute to impaired SIRT3 activity in heart failure." (PMID 27790619, 2016). "Regulation of the FOXO3/Mst1/Sirt3/AMPK axis inhibited cardiomyocyte apoptosis, enhanced mitochondrial autophagy, and ameliorated myocardial fibrosis and cardiac insufficiency in DCM." (PMID 41276460, 2025). "In heart failure rats, we also observed significant increases in p-AMPK and SIRT3 under Lig treatment." (PMID 38877519, 2024). "Our previous studies suggested Sirtuin 3 (SIRT3) as a potential target for cardiac fibrosis and heart failure." (PMID 37408261, 2023). "In Sirt3−/− mice with heart failure, Resveratrol has been shown to ameliorate cardiac fibrosis by SIRT3-dependent inhibition of TGF-β/α-SMA signaling in heart failure." (PMID 35369299, 2022). "In wild-type and Sirt3KO mice, we performed TAC operation or sham operation to establish pressure overload-induced heart failure model groups (WT-TAC group and Sirt3KO-TAC group) and control groups (WT-sham group and Sirt3-KO-sham group)." (PMID 35592397, 2022). "In DOX-induced heart failure mice, SOD2, GPx-1, FOX3a, and SIRT3 expression are decreased, apoptotic cells and cleaved-caspase-3 expression are increased, as well as inflammatory cytokines such as IL-1β, IL-6, and TNF-α are increased." (PMID 34513812, 2021). "Low expression of SIRT3 resulted in myocardial NAD+ depletion, mitochondrial enzyme acetylation, and heart failure, indicating that SIRT3 is pivotal for the maintenance of mitochondrial homeostasis." (PMID 30200365, 2018). "Second, different sirtuin isoforms, mainly SIRT3 and SIRT6, might be considered as mitochondrial markers of heart failure and require future dedicated studies." (PMID 38255934, 2024). "However, there are likely additional contributing factors since complete KO of SIRT3 causes less severe hyperacetylation than Fxn-KO, and it should be noted that recent work indicates that the hyperacetylation of mitochondrial proteins per se is not causal in heart failure." (PMID 39171530, 2024). "Melatonin enhanced myocardial mitochondrial dynamics and Sirt3 expression in CHF rats and may represent a promising upcoming therapy added to conventional heart failure treatment." (PMID 38182706, 2024). "In contrast, a recent study showed that extreme acetylation of the cardiac mitochondrial proteome in carnitine acetyltransferase and Sirt3 double knock‐out (DKO) mice did not potentiate pressure‐overload‐induced heart failure." (PMID 35872650, 2022).
heart failure (continued). "SIRT3 is downregulated in the hearts of obese humans and rats as well as in HFD-fed mice, and a decreased SIRT3 activity can result in mitochondrial hyperacetylation and subsequent ventricular dysfunction and heart failure." (PMID 33806509, 2021). "In the early stage of heart failure, the expression of SIRT1/SIRT3 in the myocardium may be stimulated by chemical and mechanical factors to compensate the functional lost." (PMID 31866862, 2019). "However, a recent study employing a carnitine acetyltransferase/Sirt3 double knock-out model argues that hyperacetylation of the mitochondrial proteome alone does not culminate in heart failure." (PMID 35369299, 2022). "However, there is a lack of understanding as to how SIRT3 gene expression is affected by altered metabolic (nutrient) state or heart failure." (PMID 34409084, 2021). "Thus, SIRT3 expression may be regulated by PGC-1α, and reduced expression of SIRT3 in heart failure may thus be related to downregulation of PGC-1α in failing hearts." (PMID 27790619, 2016).
Insulin resistance (68 papers, 2011 to 2026). Increased resistance towards insulin, that is, diminished effectiveness of insulin in reducing blood glucose levels. "Sirt3 gene deletion causes insulin resistance as shown by the hyperinsulinemic-euglycemic clamp technique, and defective glucose uptake in skeletal muscle." (PMID 36675125, 2023). "SIRT3 KO mice display insulin resistance caused by increased oxidative stress, activation of stress kinase JNK, and decreased respiration." (PMID 37006625, 2023). "Nevertheless, a deficiency of SIRT3, which is a type of sirtuin, has been shown to lead to insulin resistance and steatohepatitis, and SIRT3 polymorphisms seemed to lead to NAFLD." (PMID 37999211, 2023). "Under high fat diet or diabetic conditions, SIRT3-KO mice show increased susceptibility to insulin resistance." (PMID 35369299, 2022). "Taken together, our results show that pharmacologic activation of Sirt3 by HNK increased adipogenesis, suggesting Sirt3 inducers to be good candidates for improving insulin sensitivity and decreasing the risk of insulin resistance." (PMID 35409099, 2022). "Loss of mitochondrial Sirt function, especially Sirt3, has been linked to several age-related pathologies including cancer, insulin resistance, heart disease, fibrosis, and neurodegeneration." (PMID 36160705, 2022). "SIRT3 deficiency has been implicated in the pathogenesis of aging and age-related metabolic dysfunction such as cardiovascular disease, fatty liver, insulin resistance and type 2 diabetes." (PMID 32722262, 2020). "Numerous reports have exhibited that SIRT3 regulates mitochondrial function and maintains redox homeostasis; therefore, the impairment of SIRT3 function is implicated in the pathogenesis of insulin resistance and T2DM." (PMID 30972029, 2019). "Data from our current study revealed that ALDH2 counteracts insulin resistance-induced cardiomyopathy (myocardial, cardiomyocyte function and intracellular Ca2+ handling) possibly in association with regulation of Sirt3 and mitochondrial integrity." (PMID 27634872, 2016). "Taken together, our data suggest that ALDH2 serves as an indispensable cardioprotective factor against insulin resistance-induced cardiomyopathy with a mechanism possibly associated with facilitation of the Sirt3-dependent PGC-1α deacetylation." (PMID 27634872, 2016). "As the predominant mitochondrial NAD+-dependent deacetylase, SIRT3 serves as a metabolic gatekeeper, and is consistently found to be downregulated in clinical diabetic tissues, where its deficiency correlates with insulin resistance and disturbances in systemic energy homeostasis." (PMID 40860195, 2025). "This reduction of adipogenesis by Sirt3 inhibitor was associated with increased proinflammatory cytokines including IL6, resistin, and TNF, suggesting Sirt3 downregulation might increase the risk of insulin resistance and metabolic abnormalities." (PMID 35409099, 2022). "For instance, SIRT3 deficiency has been reported to increase insulin resistance, diabetic cardiac dysfunction, allograft graft injury, and lung fibrosis, but had no impact on innate immune responses and susceptibility to endotoxemia or bacterial and fungal sepsis." (PMID 28894448, 2017). "SIRT3 deficiency increases allograft graft injury, diabetic cardiac dysfunction, insulin resistance, acute kidney injury and lung fibrosis, suggesting that SIRT3 may counteract the development of chronic metabolic and inflammation-related disorders." (PMID 28634345, 2017). "In the present study, we investigate whether angiotensin II-induced insulin resistance in skeletal muscle is associated with Sirt3 dysregulation and whether pharmacological manipulation of Sirt3 confers protection." (PMID 25993470, 2015). "Therefore, the hyperinsulinemia of these mice may be attributed at least in part to SIRT3 deficiency caused insulin hypersecretion from β-cells, which accelerates the development of insulin resistance and metabolic syndrome." (PMID 30683850, 2019).